TNF (tumor necrosis factor)
Diseases named in the same sentence as TNF in open-access papers (continued):
Sharing a sentence is not in itself a finding about the gene and the disease.
psoriasis (continued). "Both psoriasis and metabolic syndrome (MetS) are characterised by an inflammatory T cell-mediated process, with over-expression of pro-inflammatory cytokines, tumour necrosis factor (TNF)-a, and interleukin (IL)-6." (PMID 32550048, 2020). "It correlates with IL-6 and TNF-α in the blood of patients with psoriasis." (PMID 32899610, 2020). "Since CD200 over expression in psoriasis is likely mediated by higher levels of TNFα and INFγ, both of which contribute to the cytokine inflammatory storm in psoriasis, then difference in expression levels among different severities could be explained." (PMID 32203537, 2020). "In addition, in vitro stimulation of IFN-γ and TNF-α production is decreased in NK cells from psoriasis patients relative to NK cells from healthy controls." (PMID 32917058, 2020). "The anti-TNF drug seems to affect TGFβ cascades to a greater extent than cyclosporin A. The obtained results suggest that the regularity of taking the drug is important for the efficacy of psoriasis therapy." (PMID 32774143, 2020). "The cytokines of TNF-α and IL-6 play an important role in the development of psoriasis." (PMID 32448273, 2020). "Anti-tumor necrosis factor (TNF)-α monoclonal antibodies are a class of drugs widely used in the treatment of autoimmune and inflammatory dermatological diseases, such as psoriasis, hidradenitis suppurativa as an off-label therapy, in BP, and pemphigus vulgaris (PV)." (PMID 33050407, 2020). "PP is a particular type of psoriasis induced by anti-TNF-α drugs that may occur either de novo, or as an aggravation of pre-existent lesions." (PMID 33114187, 2020). "Interestingly, medium and high doses in G3–G4, with comparatively low levels of IL-22 and TNF-α, showed stronger anti-psoriasis-like symptoms." (PMID 33253155, 2020). "Topical vitamin D is effective for psoriasis: it suppresses hyperproliferation in keratinocytes, and decreases the infiltration of Th17 cells and suppresses the expression of IL-12/23 p40, IL-1α, IL-1β, or TNF-α in the skin lesions." (PMID 32751360, 2020). "However, a recent report shows that psoriasis patients treated with anti-TNF-α antibodies experience weight gain." (PMID 32397568, 2020). "However, the significant increase of TNF-α serum level at day 2 is correlated with the appearance of psoriasis phenotype and the important increase in spleen length." (PMID 32825447, 2020). "Classical psoriasis is a T-cell mediated autoimmune disease driven by TNF, while in contrast, PP is caused by the absence of TNF and represents a type-I interferon (IFN)-driven innate inflammation." (PMID 33114187, 2020). "Results from a pooled analysis conducted by us also indicated that levels of interferon-γ, IL-17, IL-23, and tumor necrosis factor-α were significantly increased, whereas those of IL-4 and IL-10 were significantly decreased in the sera of patients with blood-heat syndrome of psoriasis." (PMID 32228720, 2020). "TNF-α is a pro-inflammatory cytokine and a key contributor to the pathogenesis of psoriasis." (PMID 33023184, 2020). "Interestingly, two other approved therapeutics for psoriasis, broadalumab (anti-IL-17A) and etanercept (anti-TNF), also downregulate KLK-7 mirroring apremilast-induced effect, thus providing plausible explanations of converged therapeutic mechanism." (PMID 31953524, 2020). "Finally, to confirm the participation of mononuclear phagocyte in the inflammation of psoriatic lesion we detected TNF-producing mononuclear cells within lesions of psoriasis patients." (PMID 32269570, 2020). "Furthermore, anti-TNFα or TNFα inhibitor treatment has been demonstrated to be a very effective treatment for psoriasis." (PMID 32153574, 2020). "Psoriasis was initially thought to be a IFNγ related disease but more recent studies—and the success of biologics targeting the IL-17 pathway—indicate a more dominant role for TNFα and IL-17 driven disease." (PMID 32153574, 2020).
psoriasis (continued). "In parallel, the anti-IL-23p40 antibody (Ustekinumab) and anti-IL-23p19 antibodies (guselkumab, risankizumab, and tildrakizumab) exhibit a high efficacy to psoriasis with a superiority of risankizumab over ustekinumab, and guselkumab over the anti-TNF-α antibody adalimumab." (PMID 32070069, 2020). "Furthermore, Cl-amidine-treated Il36rn−/− mice with psoriasis-like lesions showed decreased TNF-α, CXCL1, IL-1β, IL-36γ, and IL-17A expression compared to those in untreated, IMQ-induced Il36rn−/− mice." (PMID 33214582, 2020). "The psoriasis onset may be at any moment after anti-TNF agents’ initiation, but IBD activity appears to be in remission at the time of the onset." (PMID 32842528, 2020). "However, it has been documented that TNF contribute to vulgar psoriasis presentation, considering that targeting TNF using biologics improves symptoms." (PMID 32269570, 2020). "Data, although limited, are available suggesting that live-attenuated vaccines may be safe for individuals on tumor necrosis factor-alpha inhibitors for psoriasis." (PMID 32258339, 2020). "However, as psoriasis is an IL-17A dominated disease, we added IL-17A, IL-22, TNF-α and IFN-γ to our psoriasis-like HPKs." (PMID 32316273, 2020). "In psoriasis, IL-17+ IFN-γ+ CD4+ lymphocytes as well as high levels of IL-17, IFN-γ, and TNFα in the blood could suggest the presence of pathogenic Th17 cells and the existence of a systemic component." (PMID 32801996, 2020). "Interestingly, the treatment of psoriasis with anti-TNFα therapy led to a decrease in GlycA levels and vascular inflammation in close parallel with reductions in atherosclerotic CVD activity." (PMID 32012794, 2020). "Initially, it was speculated that TH1-derived exosomes transport cytokines such as TNF to neighboring antigen-presenting dendritic cells thereby promoting early development of psoriasis." (PMID 33291683, 2020). "Endothelial function, which is significantly altered in psoriasis patients, may also improve during treatment with TNF-alpha inhibitors." (PMID 32942670, 2020). "Finally, we generated psoriasis-like keratinocytes by treating HPKs with cytokines that are involved in the pathogenesis of psoriasis (IL-17, TNF-α, IL-22 and IFN-γ), and studied the effects of GE treatment on the expression of ELOVLs and CERS3." (PMID 32316273, 2020). "Endothelial function, which is significantly altered in psoriasis patients, may also improve during treatment with tumor necrosis factor alpha (TNF-alpha) inhibitors." (PMID 32942670, 2020). "Considering the critical role of TNF and type-I IFN in the pathogenesis of classical and paradoxical psoriasis, polymorphisms in these genes might play a role in the pathogenesis of the two diseases." (PMID 33114187, 2020). "Adalimumab, a monoclonal antibody directed against tumor necrosis factor-α, already approved for psoriasis and other various rheumatological and gastroenterological diseases, is the only biologic agent currently available for the treatment of moderate-to-severe HS resistant to antibiotics." (PMID 33182701, 2020). "The activation of the CB1 receptor (for which CBD is a weak agonist) in keratinocytes of patients with psoriasis, as well as after UV irradiation, may increase ROS production and the response of pro-inflammatory TNFα synthesis." (PMID 32121131, 2020). "Long-term anti-TNF-alpha therapy was related to BMI elevation in psoriasis patients." (PMID 32942670, 2020). "In addition, in the initiation phase of psoriasis, pDCs release the inflammatory mediators IFNα and IFNβ, thereby stimulating the secretion of pro-inflammatory mediators (such as IL-12, IL-23, and TNF) by myeloid DCs." (PMID 32013194, 2020). "It is possible that they are true cases of TNF-alpha inhibitor-induced uveitis, and thus, use of TNF-alpha inhibitor could be one of the explanations for the increased prevalence/incidence of uveitis among patients with psoriasis." (PMID 32724820, 2020).
psoriasis (continued). "Consequently, the transcription and production of a myriad of inflammatory mediators is suppressed; of concern here are TNFα, IL‐1, and IL‐17; all of which are key mediators of inflammation in psoriasis." (PMID 32203537, 2020). "Increased levels of TNF, IL-1β, and IL-22 augment the inflammatory effects of IL-17 by enhancing the expression of TNF receptors, suggesting a synergistic interplay between these cytokines in psoriasis pathogenesis." (PMID 31295952, 2019). "Some features of CD11b deficiency like enhanced activation of NFκB and other TLR-dependent pathways, Th-17 cells expansion, higher activity of DCs and production of some pro-inflammatory cytokines, e.g. IL-1β, IL-6, IL-12, IL-23, and TNF-α, are observed in psoriasis." (PMID 31211819, 2019). "TNF-a was initially designed as a treatment for inflammatory joint disorders and psoriasis but was then found to significantly improve symptoms of depression in patients with psoriasis." (PMID 31214060, 2019). "Finally, altered serum values of tumour necrosis factor alpha (TNF-α) and interleukin- (IL-) 6 have been found as important markers in obese patients with psoriasis diagnosis." (PMID 31275060, 2019). "In patients treated with anti-IL-17A monoclonal antibodies for psoriasis, routine serial repeat QFT-GIT testing was associated with lower seroconversion rate compared to real-world data of tumor necrosis factor-α inhibitors and anti-IL-12/23 antibody in Taiwan and in pivotal studies." (PMID 31881026, 2019). "Furthermore, the financial cost of treatment with the anti-TNF drugs is considerably higher than traditional systemic therapies for psoriasis such as phototherapy and methotrexate." (PMID 31120955, 2019). "Results suggest that the anti-inflammatory activity observed following exposure of hPBMCs to naringin and sericin (24 h) could be via suppression of mRNA expression and production of TNF-α, IL-6, IL-12p40 and IL-23 cytokines in psoriasis patients." (PMID 31291937, 2019). "Besides the local changes TNF, IFNγ, IL-2, IL-17, and IL-22 levels were found to be increased in serum of psoriasis patients." (PMID 31295952, 2019). "Given the good clinical response to anti-IL 17 and anti-TNF drugs in psoriasis and HS treatment, investigations into this direction could represent a starting point for a new therapeutic approach for revolutionary treatment of two difficult to treat diseases." (PMID 33456757, 2019). "Many reports have suggested that TNF-α is critical in the pathogenesis of contact dermatitis and psoriasis; therefore, therapeutic strategies based on TNF-α may be useful for these diseases." (PMID 30718736, 2019). "The different pathogenic mechanisms may also impact on treatment response, e.g., guttate psoriasis is less responsive to treatment with anti-TNF antibodies than plaque-type psoriasis." (PMID 31417571, 2019). "Furthermore, anti-TNF therapy by biological agents constitutes a first-line treatment of moderate-to-severe psoriasis." (PMID 31252620, 2019). "In turn, this may indicate that in patients for whom clinical response plateaus at a lower drug level, alternative non-TNF pathways possibly play a greater role in driving their psoriasis." (PMID 30130616, 2019). "To investigate the effect of astilbin on cell growth in HaCaT cell lines, we initially stimulated HaCaT cells with IL-17 and TNF-α, the pro-inflammatory cytokines which may contribute to the pathophysiology of psoriasis." (PMID 31492195, 2019). "TNF-α is known to be able to stimulate keratinocyte proliferation and also recruitment of T-cells to the skin, therefore propagating the inflammatory pathway of psoriasis." (PMID 31316526, 2019). "Based on clinical data IL-36 cytokines may have a role in psoriasis as expression of IL-36γ is significantly upregulated in both serum and skin lesions of patients with PV and is normalized upon anti-TNFα treatment." (PMID 31235749, 2019).
psoriasis (continued). "Of 1200 psoriasis genes, about 600 were normalized at 2 weeks by ixekizumab, but only about 100 were normalized by etanercept, translating into an improvement of 70% with IL-17 inhibition versus 35% with TNF inhibition." (PMID 31673756, 2019). "Interestingly, psoriasis patients receiving anti-TNF treatment exhibited decreased vascular inflammation and a gender-dependent effect on carotid plaque progression after 1 year." (PMID 32010143, 2019). "TNF-α, the levels of which are elevated in the serum and skin, especially in patients with AD, is thought to play an important role in the regulation of inflammation in AD and psoriasis." (PMID 31398908, 2019). "IL-1α and IL-1β cytokines stimulate the release of chemotactic cytokines such as IL-8, either directly or in synergy with TNF-α and are involved in the pathologies of several skin diseases including psoriasis, cutaneous lupus erythematosus, atopic dermatitis, and autoimmune blistering diseases." (PMID 31001258, 2019). "In psoriasis, numerous effector cells including keratinocytes, Th17 cells, and dendritic cells activated by TNF-α, plasmin and TLRs could produce cytokines and chemokines via the NFκB pathway, which leads to psoriatic phenotypes." (PMID 31824416, 2019). "Interestingly, the results of the present study revealed a significant increase in the expression and production of TNF-α level from the hPBMCs from patients with psoriasis compared with healthy subjects." (PMID 31291937, 2019). "The induction fold of TNF-α following exposure to naringin or sericin alone was significantly lower than the untreated hPBMCs from psoriasis patients (16.14, 17.3 and 30.22 fold, respectively) and the effect was more prominent with naringin/sericin combination (5.12 fold)." (PMID 31291937, 2019). "Although type 1 DM may not contribute to the pathogenesis of psoriasis directly, the TNF-α/IL-23/IL-17 axis plays a crucial role in the pathogenesis of psoriasis and type 1 DM." (PMID 31491865, 2019). "Another 45% of patients with anti-TNF-α induced psoriasis may present persistent or recurring cutaneous lesions, despite BA discontinuation." (PMID 30971924, 2019). "For moderate to severe psoriasis, several monoclonal antibodies have been approved for the treatment, including tumor necrosis factor-α (TNF-α) inhibitors, an anti-interleukin (IL)-12/23 antibody, anti-IL-23 agents, an IL-17 receptor blocker, and IL-17A inhibitors." (PMID 31881026, 2019). "The TNF-α- and IL-23/Th17-dependent pathways are regarded as vital for psoriasis development." (PMID 31137673, 2019). "Results of the study confirmed the superior activity of naringin/sericin combination compared with each compound alone on down-regulation of the pro-inflammatory cytokines including IL-6, IL-12p40, IL-23 and TNF-α related to early inflammation mechanisms of psoriasis pathogenesis." (PMID 31291937, 2019). "Interestingly, TNFα, INFγ, and IL-17A, which are the main effector of the Th1/Th17 response in psoriasis pathogenesis, also resulted to stimulate the IL-33 release." (PMID 31736655, 2019). "Furthermore, ghrelin seems to exert anti-inflammatory effects in contact dermatitis and psoriasis through suppression of NF-κB signaling, which acts as downstream of TNF-α." (PMID 30718736, 2019). "It was observed that, after anti-CD3 and anti-CD28 stimulation, IL-10 levels were significantly lower in psoriasis patients treated with methotrexate and in patients on anti-TNF treatment than in healthy control subjects (p = 0.029 and p = 0.030, respectively)." (PMID 31101850, 2019). "In addition, in the psoriasis mouse model, lower dose of IL‐35 recombinant protein can achieve long‐term therapeutic effects as TNF‐α monoclonal antibody did." (PMID 29193791, 2018). "Thus, uniform high levels of type I IFN expression in lesional skin characterize anti-TNF-induced paradoxical psoriasis." (PMID 29295985, 2018).
psoriasis (continued). "A higher frequency of CARD14 variants, in particular the common p.R820W polymorphism, were found among responders to TNFα-targeted blockade, suggesting that CARD14-associated psoriasis could benefit from anti-TNF treatment." (PMID 30386326, 2018). "In psoriasis, we have found that IL-17E, produced by epidermal keratinocytes in the lesional skin, activates dermal macrophages to produce inflammatory cytokines, including TNF, and neutrophil chemokines, such as IL-8." (PMID 30127781, 2018). "Thus, paradoxical psoriasis is a side effect of an anti-TNF treatment stemming from an overactive, but self-limiting innate inflammation driven by pDC-derived type I IFN." (PMID 29295985, 2018). "In psoriasis, pro-inflammatory cytokines including IL-17A, IL-22, TNF-α and IL-1α may contribute to the pathophysiology of the disease." (PMID 30180891, 2018). "Activated macrophages in adipose tissue stimulate adipocytes to secrete TNF-α, IL-1, IL-6, and IL-8, which may contribute to the development of psoriasis." (PMID 29680995, 2018). "Furthermore, the yin-yang of TNF and type-I IFN, the pathogenic mechanism underlying paradoxical psoriasis, is inherently true for healthy individuals as much as patients." (PMID 30555460, 2018). "Anti-TNF-induced paradoxical psoriasis appeared independent of the underlying diseases or the type of anti-TNF agent used." (PMID 29295985, 2018). "IL-17A acts in synergism with other key-cytokines in psoriasis such as TNF-α and IL-22, stimulating the expression AMPs (LL37, β-defensins, LCN2, S110A family proteins), inflammatory cytokines (IL-1 family members and IL-6), and chemokines (CXL1, -3, -5, -8, and CCL20)." (PMID 29316717, 2018). "Moreover, piclidenoson induced a decrease in the expression level of PI3K, p-AKT, NF-κB, TNF-α, IL-17, and IL-23, known to act as potent inflammatory mediators in psoriasis." (PMID 29862305, 2018). "The involvement of a large surface skin area in psoriasis patients intensifies the role of factors such as NF-κB and TNF-α, leading to amplification of the inflammatory process, which may also attribute to A3AR overexpression." (PMID 29862305, 2018). "Compound 5c could be used as a candidate immunomodulatory agent in inflammatory skin disease, especially in psoriasis; however, its use in the case of TNF-α-overexpressing skin disease should be further investigated." (PMID 30301277, 2018). "Moreover, many molecularly targeted drugs for psoriasis and AD—TNF, IL-12/IL-23p40 subunit, IL-23p19 subunit, IL-17A, IL-17RA, and IL-4Rα—have been developed." (PMID 29642409, 2018). "Thus, proinflammatory cytokines, such as TNF-α and IL-17, are considered the therapeutic targets for the treatment of psoriasis." (PMID 30258447, 2018). "In psoriasis, TNF is an important activator of IL-23 expression." (PMID 29650963, 2018). "Importantly, TNF-α induces IL-36γ in psoriasis lesions, which in turn promote expression of AMP and chemokines recruiting neutrophils and Th17 cells, as well as interfere with terminal differentiation and cornification process of psoriatic epidermis." (PMID 30034395, 2018). "Here, the authors show that anti-TNF drugs enhance the production of type I interferon by plasmacytoid dendritic cells, causing skin lesions that, unlike classical psoriasis, lack T- cell autoimmunity." (PMID 29295985, 2018). "In psoriasis, e.g., TNF-a, IL-17, and IL-23, are increased in the skin and may play a role in chronic pruritus of psoriatic patients." (PMID 30560129, 2018). "A diet and exercise intervention was also found to reduce concentrations of TNF-α, IL-6, IL-8, C-reactive protein and monocyte chemoattractant protein 1, which may contribute to improvement of psoriasis." (PMID 29680995, 2018). "In contrast, paradoxical psoriasis is caused by the absence of TNF and represents an ongoing type-I interferon-driven innate inflammation that fails to elicit T-cell autoimmunity and lacks memory T cell-mediated relapses." (PMID 30555460, 2018).